DENND4B (DENN domain containing 4B)
Description:
Guanine nucleotide exchange factor (GEF) which may activate RAB10. Promotes the exchange of GDP to GTP, converting inactive GDP-bound Rab proteins into their active GTP-bound form.
Synonyms: KIAA0476
Tractability: PROTAC: ubiquitination databases record sites on it; its protein half-life has been measured.
Gene: Protein-coding gene on chromosome 1 (153,928,864 to 153,946,744, reverse strand). Ensembl gene ENSG00000198837.
Subcellular location: Golgi apparatus
Subcellular location (Human Protein Atlas): Golgi apparatus; Nucleoplasm
Pathways (Reactome):
Vesicle-mediated transport: RAB GEFs exchange GTP for GDP on RABs
Gene Ontology:
Molecular function: guanyl-nucleotide exchange factor activity
Biological process: regulation of Rab protein signal transduction
Cellular component: Golgi apparatus; cytosol
Genetic constraint (gnomAD): Loss-of-function variants: 67 observed, 155.67 expected, observed/expected ratio (o/e) 0.43, 90% interval 0.35 to 0.53. The upper end of that interval is the gene's LOEUF score, 0.53, which puts it in group 2 of 6, group 1 being the genes least tolerant of losing a copy. Missense variants: 1,478 observed, 1,967.3 expected, observed/expected ratio (o/e) 0.75, 90% interval 0.72 to 0.78. Synonymous variants: 752 observed, 809.17 expected, observed/expected ratio (o/e) 0.93, 90% interval 0.88 to 0.99.
Homologues: Orthologues: chimpanzee DENND4B (99% identical), macaque DENND4B (98% identical), rabbit DENND4B (95% identical), pig DENND4B (95% identical), dog DENND4B (94% identical), mouse Dennd4b (94% identical), rat Dennd4b (94% identical), guinea pig DENND4B (93% identical), tropical clawed frog dennd4b (57% identical), zebrafish dennd4b (55% identical), Drosophila melanogaster Crag (35% identical), Caenorhabditis elegans denn-4 (31% identical). Paralogues in human: DENND4A (46% identical), DENND4C (44% identical), DENND3 (13% identical).
Diseases named in the same sentence as DENND4B in open-access papers:
DENND4B is named in the same sentence as 2 diseases in open-access papers, as found by Europe PMC text mining. Sharing a sentence is not in itself a finding about the gene and the disease. The quoted sentences say what the papers report.
pancreatic cancer (1 paper, 2021). "A total of 8 immune genes (ITGA7, RBM14, DENND4B, LQK1, ZNF709, COL7A1, SP1, NCBP2) were identified as independent prognostic factors of pancreatic cancer, which were used to construct a clinical predictive model." (PMID 33546693, 2021).
DENND4B also shares sentences with these, for which no sentence is quoted: chronic pancreatitis (1 paper).